STAT3 (signal transducer and activator of transcription 3)
Diseases named in the same sentence as STAT3 in open-access papers (continued):
Sharing a sentence is not in itself a finding about the gene and the disease.
breast cancer (continued). "Recent studies indicated that the activation of LIFR and downstream STAT3 signaling maintained breast cancer cells in a dormant state and that loss of the LIFR-STAT3 axis led to enhanced proliferation of cancer cells and to bone destruction." (PMID 36925915, 2023). "STAT3 induces the secretion of STC1 from tumor-associated fibroblasts to foster breast cancer growth." (PMID 37400459, 2023). "High levels of EZH2 are not only associated with breast cancer tumor immune response, Ezh2 also acts with Stat3 as a transcriptional activator to alter the tumor immune response in melanoma." (PMID 37853322, 2023). "IL-11 activates osteoclastogenesis in breast cancer bone metastasis-associated osteolysis through the JAK1/STAT3/c-Myc pathway." (PMID 37199584, 2023). "STAT3 is linked to tumor progression in a wide variety of cancers, and its expression promotes invasion and metastasis in ovarian and breast cancer." (PMID 37558923, 2023). "A small study of a retrospective cohort of 102 breast cancer patients identified an association between high expression of STAT3 within tumour cells with reduced overall survival." (PMID 37199043, 2023). "Higher expressions of SOCS1, 3, 4, and 7 are associated with good prognosis in breast cancer, and STAT3 is constitutively activated in breast cancer." (PMID 37064130, 2023). "The change in STAT3 leads to abnormal cell proliferation and malignant metastasis in breast cancer, and disrupting STAT3 activation progression causes an apparent inhibiting of breast cancer effect." (PMID 37173892, 2023). "For example, FABP4 facilitates the stemness and aggressiveness of tumour cells via the IL-6/STAT3/ALDH1 axis in obesity-associated breast cancer." (PMID 35198079, 2022). "High expression of TNFRSF1A was demonstrated to be associated with STAT3 activation in breast cancer cells, where STAT3 is known as a critical factor in tumorigenesis." (PMID 36035315, 2022). "On the other hand, in ER(+) breast cancer, p-STAT3 overexpression was associated with a favorable prognosis (p = 0.034, HR 9.48, 95%CI 1.18–76.21)." (PMID 35314590, 2022). "Demodulation of Jak, stat 3 and Akt signalling along with MAP kinase pathway cause paclitaxel resistance by STAT3 in breast cancer, and also the basal activity of JAK1/STAT1 and JAK1/STAT3 signalling is higher in chemo resistant cells." (PMID 36415633, 2022). "For a long time, STAT3 or p-STAT3 overexpression in breast cancer had been reported to be linked to good prognosis, but another study reported that it was associated with poor prognosis." (PMID 35314590, 2022). "Certain studies have shown that the high expression of STAT3 in breast cancer was associated with a favorable prognosis, whereas others have suggested that it was associated with a poor prognosis." (PMID 35314590, 2022). "In those studies, STAT3 and/or p-STAT3 overexpression in breast cancer was linked to a favorable prognosis." (PMID 35314590, 2022). "In breast cancer, Stat3 is associated with triple-negative breast cancers (TNBC) and its function has been related to the activation of p63, itself a marker of basal-like TNBC and a master regulator of stem cell activities." (PMID 36017196, 2022). "Long noncoding RNA associated with breast cancer brain metastasis (lnc-BM) is upregulated in metastatic cells where it induces the expression of CCL2 via the activation of the JAK2/STAT3 pathway." (PMID 35202089, 2022). "In the present study, the role of p-STAT3 expression in breast cancer was examined, and the association between clinicopathological/biological factors and p-STAT3 expression was analyzed in each subtype." (PMID 35314590, 2022). "STAT3 is a transcription factor for breast cancer proliferation-associated genes such as CCND1, c-myc, BCL2, and BAX." (PMID 36106139, 2022). "CDYL2, including an Indel significantly associated with LTN on SSC6, positively regulates breast cancer cell migration, invasion and epithelial-to-mesenchymal transition through p65/NF-κB and STAT3." (PMID 35565484, 2022).
breast cancer (continued). "IL-6 is similarly associated with STAT3-mediated cisplatin resistance in breast cancer, and with acquired cisplatin resistance and poor prognosis in head and neck squamous cell carcinoma." (PMID 35356749, 2022). "For example, FABP4 promotes tumour cell progression via the IL-6/STAT3/ALDH1 axis in obesity-associated breast cancer." (PMID 35198079, 2022). "The association of STAT3 polymorphism rs4796793 with cancer susceptibility has been already demonstrated in lung cancer, breast cancer, hepatocellular carcinoma and cervical cancer." (PMID 32270320, 2021). "Results showed that TrkA WT-overexpressing cells had significantly higher mRNA levels of SOX2 and MYC, which are two known STAT3 target genes frequently associated with breast cancer cell stemness and aggressiveness." (PMID 34066153, 2021). "In accordance, targeting STAT3 or its signaling by nifuroxazide has also been documented to cause breast cancer cell apoptosis in 4T1 cells grown in mice via the inhibition of STAT3." (PMID 34833950, 2021). "Accordingly, leptin has been linked to the induction of telomerase activity via STAT-3 in MCF-7 breast cancer cells." (PMID 34283044, 2021). "Activated STAT3 and IL-6 are found in TN breast cancer or high-grade tumors and are associated with poor response to chemotherapy." (PMID 34771512, 2021). "Nifuroxazide has also been documented to cause breast cancer apoptosis and prevent pulmonary metastasis in mice via the inhibition of STAT3." (PMID 34833950, 2021). "Previous studies have shown that HNRNPA2B1 is overexpressed in breast cancer tissue, and that its encoded protein can activate the STAT3 and ERK1/2 signaling pathways, thereby promoting the tumorigenic potential of cancer cells." (PMID 33628845, 2021). "Recently, STAT3-deficient cDCs (STAT3− cDCs) was reported to inhibit the breast cancer growth and poor survival as a cell-based vaccine." (PMID 33957948, 2021). "STAT3 represents a common target for miR-21 which is implicated in both breast cancer pathogenesis and adipose cell proliferation and differentiation." (PMID 34199293, 2021). "miR-145 is associated with IL-6/STAT3 pathways and is under-expressed in breast cancer with high metastatic capability." (PMID 34299605, 2021). "Of note, a lot of studies have revealed that STAT3 cascade was associated with breast cancer immune responses, which can potentiate signaling in TME immune cells and tumor cells." (PMID 33957948, 2021). "In this study, we examined five cancer immunity-related pathways (IFNα, IFNγ, STAT3, TGFβ and TNFα) in four large independent breast cancer cohorts (n = 6,381) and their associations with the prognosis of breast cancer subtypes." (PMID 33767579, 2021). "Bioactivity of the rhOSM was comparable to commercially available recombinant human OSM (chOSM) in human breast cancer cells as determined by an enzyme-linked immunosorbent assay (ELISA), which detected phosphorylation of STAT3." (PMID 34376712, 2021). "They reported that STAT3 was one of the genes associated with survival in patients with breast cancer." (PMID 34407787, 2021). "Another interesting candidate is STAT3 which is activated in more than 40% of breast cancers and can cause deregulated cell proliferation and epithelial-to-mesenchymal transition (EMT)." (PMID 33706810, 2021). "For example, elevated levels of IL-6 stimulate hyperactivation of JAK/STAT3 signaling, which is often associated with poor patient outcomes in colorectal cancer, breast cancer, oral cancer, and myeloma." (PMID 34422643, 2021). "For example, the JAK2/STAT3 pathway is prominent in the progression of ovarian cancer, and it has been proven to be associated with metastasis in breast cancer." (PMID 34765550, 2021). "It is noteworthy that both STAT3 and alternative NF-κB pathways are associated with poor prognosis in breast cancer patients." (PMID 33396715, 2020).
breast cancer (continued). "STAT3 correlates with resistance to radiotherapy in HER2-positive breast cancer tissue, and radiation resistance in breast cancer stem cells is strongly associated with a high expression of STAT3." (PMID 32872659, 2020). "Abnormal STAT3 signal can cause the dysregulation of expressions of downstream genes such as Bcl-2 and promote breast cancer progression." (PMID 32760217, 2020). "This FGFR4-associated SNP is important for breast cancer susceptibility, as it causes a receptor conformational change that allows functional interaction with the signal transducer and activator of transcription 3 (STAT3)." (PMID 33081025, 2020). "Since the STAT pathway has been implicated in breast cancer metastasis to the bone, we analyzed the activation of STAT3." (PMID 32466213, 2020). "STAT3 was also reported to mediate Sox2 expression in murine breast cancer cells in response to tumor-associated macrophages." (PMID 33228022, 2020). "Docetaxel resistance have been linked to constitutive STAT3 activation and elevated survivin expression in breast cancer." (PMID 32231398, 2020). "In the MCF-7 breast cancer line, nAChR activation by nicotine led to a decrease in staurosporin-induced cell death, which was associated with activation of the α9 nAChR/STAT3/Galectin-3 pathway." (PMID 32272633, 2020). "A study demonstrated that in breast cancer cells, phosphorylated STAT3 up-regulates the EMT associated protein, TWIST." (PMID 32391382, 2020). "The underlying mechanisms of lovastatin in inactivating STAT3 in breast cancer cells remain unresolved." (PMID 31821701, 2020). "Compared with other breast cancer subtypes, STAT3 is most often associated with triple negative tumors, which are rich in cancer stem cells." (PMID 32391382, 2020). "STAT3 signaling is a well-known driver of breast cancer and CSCs, and is associated with worse relapse-free survival." (PMID 33266219, 2020). "STAT3 pathway and β-catenin signaling are frequently dysregulated in breast cancer, contributing to cancer stem cells (CSCs)-associated tumor initiation, angiogenesis, metastasis, therapy resistance, and tumor relapse." (PMID 32887217, 2020). "In the case of breast cancer, the expression of phosphorylated Stat3 (p-Stat3) has been proven to be high and is associated with breast cancer progression and/or development." (PMID 31649548, 2019). "The increased expression of STAT3 and downstream targets, such as Survivin, has been demonstrated in multiple murine models of breast cancer, as well as patient tissues, and it has been linked to immune evasion during both tumorigenesis and metastasis." (PMID 31842362, 2019). "MH causes a rapid loss of p-STAT3 in human breast cancer cells, reducing their proliferation, migration, and invasiveness." (PMID 31491838, 2019). "Here, we will discuss the signal transducer and activator of transcription 3 (Stat3) signaling pathway, which has also been implicated in different types of human tumors, including melanoma, lung cancer, colorectal cancer, and breast cancer." (PMID 31649548, 2019). "In order to explore the important factors in the diagnosis of breast cancer in China, meta-analysis of previous studies was performed to understand the association between STAT3/p-STAT3 and breast cancer." (PMID 31375715, 2019). "Although the induction of cell proliferation and cell survival genes by STAT3/5 proteins contribute to their pro-cancer activity, in basal-like breast cancers the major genes associated with STAT3 activation control inflammation and the immune response." (PMID 31557897, 2019). "Nevertheless, in our model system, exposure of breast cancer cells to MH leads to a rapid loss of >80% of activated p-STAT3 protein, which is also associated with decreased gp130 and p-JAK2 levels." (PMID 31491838, 2019). "The association between PD-L1 and STAT3 expression was first assessed in human breast cancer cell lines." (PMID 31581535, 2019).
breast cancer (continued). "The mTOR/STAT3 signaling pathway has been reported as a requirement for the growth of stem cell-like breast cancer SP cells, and it is implicated in the mediation of WA-induced apoptosis." (PMID 31319622, 2019). "Tamoxifen-resistant breast cancers have elevated STAT3 and Notch4 expression associated with metastasis and tumorigenicity." (PMID 31684144, 2019). "Honokiol modulated microRNA profile in the breast cancer cell, specifically amplifying miR-34a expression in a STAT3-dependent manner, inhibiting Wnt1-metastatic-associated protein 1 (MTA1)-β-catenin signaling axis." (PMID 30134816, 2018). "High STAT3 mRNA level showed a significant association with OS (HR =0.68 (0.49–0.93), P=0.014) in breast cancer patients." (PMID 29326301, 2018). "Another intriguing possibility is that loss of STAT3 signaling is necessary for disseminated breast cancer cells to exit from a dormant state, as recently suggested by Giaccia’s group." (PMID 30231553, 2018). "Recent studies have also reported that activated Stat3 were closely associated with the development of breast cancer." (PMID 29423083, 2018). "Stat3 activation is found in all classes of breast cancers, but is most often associated with triple negative breast tumors." (PMID 30297887, 2018). "It has also been implicated as the main mediator of STAT3 activation in various breast cancer cell lines." (PMID 29867925, 2018). "RKIP overexpression was reported to reverse STAT3-dependent prostate and breast cancer invasive and migratory properties, through a direct constitutive physical interaction with STAT3 that blocks c-Src and STAT3 association, needed for STAT3 activation." (PMID 30149591, 2018). "Constitutive activation of STAT3 was reported in more than 60% of breast cancers and was associated with poor prognosis." (PMID 30013043, 2018). "Consistently, loss or depletion of STAT3 in breast carcinoma cells has been shown to result in tumor inhibition and induction of apoptosis." (PMID 29934528, 2018). "Signal transducer and activator of transcription 3 (STAT3) is a potential modulator of chemotherapeutic resistance in the model of APC loss in breast cancer." (PMID 29262529, 2017). "Our previous study identified that in breast cancer cell, persistent activation of STAT3 for EMT was partly caused by a positive feedback autocrine loop of PIM-dependent secreted cytokines." (PMID 29254164, 2017). "Activation of signal transducer and activator of transcription-3 (STAT-3) is associated with the up-regulation of survivin in gastric cancer, breast cancer, and primary effusion lymphoma." (PMID 28536639, 2017). "Activation of mTOR/STAT3 signaling has been linked to the development and progression of cancers such as breast cancer, gastric cancer and liver cancer." (PMID 29016699, 2017). "Subsequent study demonstrated that the activation of extracellular-signal regulated kinase and signal transducer and activator of transcription 3 of DCs caused by CTLA-4+ breast cancer cells were the predominant mechanism of DC suppression." (PMID 28099147, 2017). "STAT3 loss in MT/ShcA+/+ breast cancer cells severely impaired tumour incidence in CD8+/+ mice (100% versus 25% tumour-bearing mice)." (PMID 28276425, 2017). "Taken together, these data demonstrate for the first time the roles of CSE in breast cancer leading to breast cancer development in association with STAT3 signaling pathway." (PMID 29029463, 2017). "MDA-MB-231 cells are known to express constitutively activated STAT3 pathway, principally through the engagement of an IL-6/IL-6R autocrine loop, and this pathway has been implicated in breast cancer oncogenesis." (PMID 28856117, 2017). "In summary, we demonstrated for the first time that CSE/H2S system promoted breast cancer development and progression in association with the STAT3 signaling pathway." (PMID 29029463, 2017).
breast cancer (continued). "This is further supported by our observation in primary human breast cancers that elevated STAT1 transcriptional responses are only associated with enhanced PD-L1 expression levels in tumours that possess a low STAT3 transcriptional signature." (PMID 28276425, 2017). "With the increase of the EMT subtype and given the previously identified role of Stat3 in breast cancer metastasis, we investigated how loss of Stat3 altered metastasis in the MMTV-Myc strain." (PMID 27589562, 2016). "STAT3 overexpression was associated with favorable 5-year OS of breast cancer (OR = 0.57, 95% CI = 0.37 to 0.89, P = 0.01)." (PMID 26959884, 2016). "Our previous study showed that SH003 at higher concentrations caused breast cancer cell death by inhibiting STAT3-mediated signaling pathway." (PMID 27105528, 2016). "A previous study suggested that STAT3 activation is correlated with survivin expression in high-risk breast cancer patients." (PMID 26755645, 2016). "We have shown that the HR−/HER2+ subtype of breast cancer is associated with radiotherapy resistance via HER2-mediated regulation of STAT3-survivin signaling." (PMID 26755645, 2016). "Among signaling pathways which crosstalk with the Wnt signaling pathway, STAT3 activation has been particularly linked with breast cancer progression." (PMID 27259262, 2016). "The results of our study demonstrate that exposure of breast cancer cells to the ES cell microenvironment downregulates Stat3 signaling, associated with a reduction in clonogenicity and tumorigenicity." (PMID 27460364, 2016). "SNP rs1905339 (A>G) in the STAT3 region was associated with an increased breast cancer risk (per allele odds ratio 1.05, 95 % confidence interval 1.03–1.08; p value = 1.4 × 10−6)." (PMID 26621531, 2016). "Nonetheless, STAT3 activity is observed in other breast cancer subtypes as well, and it is rarely mutated." (PMID 25699542, 2015). "Since STAT3 is activated in most breast cancers and associates with microtubules, Taub have shown that microtubule-targeted therapy modulates STAT3 signaling and function in breast cancer cells." (PMID 26464811, 2015). "In summary, EGFRvIII expression increased the de novo resistance of breast cancer cells against trastuzumab, and the feedback activation of STAT3 caused by trastuzumab also contributed to acquired resistance in EGFRvIII+HER2+ breast cancers." (PMID 26474285, 2015). "All four STATs have been shown to play roles in breast cancer; however, STAT3 activation has been linked to more aggressive types." (PMID 26697522, 2015). "Here, we demonstrated that EGFRvIII overexpression contributed to de novo trastuzumab resistance and the feedback activation of STAT3 caused by trastuzumab also resulted in acquired resistance in EGFRvIII+HER2+ breast cancers." (PMID 26474285, 2015). "Meta-analysis of over a thousand primary breast cancers showed that high VEGF expression is strongly associated with STAT3 and MYC expression, supporting the link between VEGFR-2 and CSC self-renewal." (PMID 26500608, 2015). "STAT3 is also associated with sphere-forming efficiency as well as cancer stem cell-like functions in nasopharyngeal carcinoma and breast cancer." (PMID 25638155, 2015). "Several kinases have been implicated in maintaining STAT3 activity in breast cancer, including EGFR, JAK2, and Src." (PMID 25699542, 2015). "Work from several laboratories indicated that the cell density can cause a sharp increase in STAT3 phosphorylation in breast carcinoma, head and neck squamous cell carcinoma, and normal epithelial cells." (PMID 26631279, 2015). "Previous investigations into the roles of the STAT family in endocrine-resistant breast cancer, especially STAT3 and STAT5, have shown associations with tumorigenicity, cell-cycle progression, cell survival, transformation, and angiogenesis." (PMID 24728078, 2014). "In fact, the association between breast cancer and aberrant Stat3 expression was established more than 10 years ago." (PMID 24416452, 2014).